PRL (prolactin)
Diseases named in the same sentence as PRL in open-access papers (continued):
Sharing a sentence is not in itself a finding about the gene and the disease.
hyperprolactinemia (continued). "Among tumors that produce PRL, the vast majority are sparsely granulated lactotroph tumors that show a very strong correlation between tumor size and degree of hyperprolactinemia." (PMID 40718390, 2025). "Namely, macroprolactinomas exhibit prolonged time of hyperprolactinemia- and thus older age at diagnosis, as the lower rates of baseline PRL levels in women probably reflects on the shorter disease duration in more evident symptoms in women." (PMID 40113928, 2025). "The beneficial effect on sexual functioning in women with prolactin excess was caused by dopamine agonists, which are the drugs of choice for prolactin-secreting tumors and symptomatic hyperprolactinemia of other origin." (PMID 40507082, 2025). "As mentioned, dopamine agonists including bromocriptine and cabergoline are used to treat hyperprolactinemia, and it has been suggested that prolactin per se plays a role in migraine pathophysiology." (PMID 40168298, 2025). "Aripiprazole has demonstrated efficacy in reducing prolactin levels and is recommended in clinical guidelines for managing antipsychotic-induced hyperprolactinemia." (PMID 40465597, 2025). "This study aims to determine the prolactin levels and anemia prevalence in infertile women of Balochistan, Pakistan, and to establish whether female infertility is related to hyperprolactinemia and anemia, in addition to the association between hyperprolactinemia and anemia in infertile women." (PMID 40535391, 2025). "In Graves-Basedow disease and hyperprolactinemia (with an aetiology of prolactin-secreting pituitary tumours and in idiopathic form), the influence of stressful life events on the pathophysiology of the disease in question has been demonstrated." (PMID 41234225, 2025). "Data from a metoclopramide (MCP)-induced hyperprolactinemia mouse model showed that oral administration of HY7801 reduced serum levels of prolactin and pro-inflammatory cytokines significantly, while restoring hormone imbalances caused by MCP." (PMID 40935392, 2025). "The patients were divided in two groups having normoprolactinemia (59.2%) and hyperprolactinemia (40.8%) according to the reference range for serum prolactin levels of the respective laboratory (125–635 mIU/L)." (PMID 40362476, 2025). "For example, it was not possible to test for an interaction between age and antipsychotic type or prolactin levels, and so conclusions about the differential effects of hyperprolactinaemia are based solely on differences between age groups." (PMID 41327590, 2025). "Acute exposure to elevated PRL levels can increase inflammation during stress, whereas chronic hyperprolactinemia tends to have an immunosuppressive effect." (PMID 41476991, 2025). "Unlike men, in whom hypolibidemia and erectile dysfunction are typical features of hyperprolactinemia, the sexual functioning of women with elevated prolactin levels has attracted much less interest." (PMID 40507082, 2025). "Although hyperprolactinemia is common among schizophrenia patients, elevated prolactin levels can often be asymptomatic." (PMID 40465597, 2025). "Hyperprolactinemia, characterized by elevated PRL levels, is primarily viewed as a pathological condition, particularly when excluding physiological instances such as pregnancy." (PMID 41476991, 2025). "Distribution of patients according to prolactin level at the time of the study: 8 patients had hypoprolactinemia, 25 patients had normoprolactinemia, and four patients had hyperprolactinemia." (PMID 39361237, 2025). "The most frequently reported side effects were increased prolactin in the blood (7.8%), headache (7.3%), hyperprolactinemia (5%), and weight gain (4.8%)." (PMID 40430486, 2025). "It should be noted that in this study, we excluded participants with hyperprolactinemia (PRL levels ≥ 100 ng/mL) to minimize the potential confounding effects of extreme prolactin elevations." (PMID 40021736, 2025).
hyperprolactinemia (continued). "DB00248 (Cabergoline) is a dopamine D2 receptor agonist approved for the treatment of hyperprolactinemia, and has been reported to normalize prolactin levels in most patients." (PMID 41256885, 2025). "Dopamine agonists, such as bromocriptine and cabergoline, remain the cornerstone of hyperprolactinemia treatment, effectively reducing prolactin levels and restoring ovulatory function." (PMID 41510476, 2025). "Prolactin is synthesized and secreted by lactotroph cells in the anterior pituitary, and the core mechanism of hyperprolactinemia is a disruption of the hypothalamic–pituitary regulatory control of prolactin secretion." (PMID 41480352, 2025). "Hyperprolactinemia, defined by elevated serum prolactin levels, arises from various etiologies, including pituitary adenomas, medication adverse effects, and systemic disorders." (PMID 40656428, 2025). "Administering dopamine agonists to patients with hyperprolactinemia is an effective therapeutic strategy, as it not only lowers excessive prolactin levels but also resolves metabolic disorders." (PMID 40362476, 2025). "Hyperprolactinemia, defined as elevated serum prolactin levels, is an endocrine disorder that frequently presents with menstrual irregularities, galactorrhea, and infertility." (PMID 41510476, 2025). "Prolactin was evaluated at the time of the blood study and categorized as normoprolactinemia (serum PRL levels < 20 ng/mL) or hyperprolactinemia (serum PRL levels > 20 ng/mL)." (PMID 39791749, 2025). "The physiological mechanisms underlying stress-induced hyperprolactinemia involve the activation of the hypothalamic-pituitary-adrenal (HPA) axis, leading to increased prolactin release." (PMID 40656428, 2025). "Hyperprolactinemia (> 530 mIU/L) was detected in one woman (5%) in the prolactin-sparing group and in 16 women (59%) in the prolactin-raising group." (PMID 38995314, 2024). "From a practical point of view, in most cases of medication-induced hyperprolactinemia, prolactin levels are below 100 ng/mL." (PMID 38578472, 2024). "Infertility treatment in patients with hyperprolactinemia is carried out with dopamine agonists, aiming for the normalization of prolactin levels." (PMID 38578473, 2024). "By contrast to the well-established area of research on hyperprolactinemia, there is a paucity of studies on the effects of low PRL levels on health outcomes." (PMID 38760578, 2024). "These symptoms are generally alleviated after hyperprolactinemia is corrected, suggesting that prolactin plays a direct role in psychological disorders." (PMID 38572480, 2024). "Except during pregnancy and breastfeeding, in which hyperprolactinemia can reach values above 200 ng/mL, the elevation of prolactin in other situations is mild and rarely leads to galactorrhea or menstrual irregularity." (PMID 38578472, 2024). "In cases of hyperprolactinemia secondary to hypothyroidism, the thyroid dysfunction must be treated first, and once the thyroid function is normal, hyperprolactinemia-related symptoms and serum prolactin levels should be reevaluated." (PMID 38578473, 2024). "Regarding hyperprolactinemia, our results show a positive correlation between prolactin levels and fatigue scores." (PMID 39233885, 2024). "Hyperprolactinaemia is regarded when PRL serum level is increased more than 20 ng/mL in men and 25 ng/mL in women." (PMID 39663784, 2024). "Antipsychotic medications are frequently responsible for hyperprolactinemia, which is the result of the blockade of dopamine receptors on prolactin-releasing cells in the anterior pituitary gland (Rubin, and T, Prolactin and schizophrenia 1987)." (PMID 38221595, 2024). "Infertility treatment of patients with hyperprolactinemia is also carried out with dopamine agonists, aiming for the normalization of prolactin levels." (PMID 38578473, 2024).
hyperprolactinemia (continued). "These medications can normalize PRL levels in nearly 90% of patients with idiopathic hyperprolactinemia or prolactin microadenomas and in 75-80% of patients with macroprolactinomas." (PMID 38572480, 2024). "Hyperprolactinemia is likely attributable to increased GHRH, which is known to cause high prolactin in normal subjects and in patients with acromegaly, due to lactotroph hyperplasia." (PMID 39449742, 2024). "The underlying mechanism of SSRI-induced DO is that serotoninergic inputs from the dorsal raphe nucleus stimulate PRL-releasing factors in the paraventricular nucleus, resulting in hyperprolactinemia and subsequent suppression of T production." (PMID 37061617, 2024). "Serum prolactin measurement should only be performed in the presence of symptoms compatible with hyperprolactinemia and/or in the presence of a pituitary tumor, even if the diagnosis is incidental." (PMID 38578472, 2024). "Prolactin should be measured in patients with acromegaly, since they often have concomitant hyperprolactinemia." (PMID 38578472, 2024). "Prolactin is an upregulator of immune processes, and hyperprolactinaemia is often present in autoimmune diseases." (PMID 39407928, 2024). "We also found that PFM and HY7801 significantly reduced the prolactin concentration in the mice with MCP-induced hyperprolactinemia." (PMID 39599674, 2024). "These tumors resemble a mammosomatotroph tumor, secreting GH and PRL, but they also express variable GATA and TSHβ, producing overt acromegaly associated with hyperprolactinemia." (PMID 38248047, 2024). "It supports the broader understanding that while antipsychotic medications can elevate prolactin levels, resulting in hyperprolactinemia, the development of actual prolactinomas is rare among this population." (PMID 38998877, 2024). "A single prolactin measurement is sufficient to establish the diagnosis of hyperprolactinemia in most cases." (PMID 38578472, 2024). "The observatory for hyperprolactinemia considers the fact that women’s baseline prolactin levels are higher than men’s and that they are more prone to anxiety, which, itself, raises prolactin levels." (PMID 39120186, 2024). "Elevated PRL (hyperprolactinemia) is the most common endocrine disorder of the hypothalamic–pituitary axis." (PMID 38396659, 2024). "According to the HomeoFIT-PRL (Homeostatic Functionally Increased Transient Prolactinemia) model, mild hyperprolactinemia with PRL levels > 25 ng/mL has been claimed to occur in response to metabolic challenges and to favor metabolic homeostasis." (PMID 39857650, 2024). "The direct correlation between serum TSH and prolactin levels suggests that hyperprolactinemia in primary hypothyroidism is primarily mediated by thyrotropin-releasing hormone release in the absence of negative feedback from T3 and T4." (PMID 39416273, 2024). "The prolactin levels in patients with hyperprolactinemia due to primary hypothyroidism (n = 73) ranged from 34 to 253 ng/mL (mean, 81.33 ± 49.34 ng/mL; median, 64 ng/mL)." (PMID 39420933, 2024). "If medication-induced hyperprolactinemia is suspected, another serum prolactin measurement is recommended 3 days after discontinuation of the drug, provided withdrawal is feasible." (PMID 38578472, 2024). "Hyperprolactinemia also leads to DO as increased levels of prolactin (PRL) result in suppression of T production." (PMID 37061617, 2024). "This suggests that in the future, a more precise treatment model for hyperprolactinemia should consider the initial prolactin levels of patients." (PMID 38505795, 2024). "The design of the present in vivo study in rats follows that of a previous similar study in mice in which hyperprolactinemia was induced by transgenic expression of prolactin." (PMID 38560358, 2024). "The highest mean prolactin levels were observed in cases of prolactinomas and idiopathic hyperprolactinemia." (PMID 39420933, 2024).
hyperprolactinemia (continued). "In conclusion, despite considerable overlap in prolactin levels among different etiologies of hyperprolactinemia, values > 250 ng/mL allowed a clear distinction between macroprolactinomas and nonfunctioning pituitary adenomas." (PMID 39420933, 2024). "Nonetheless, systematic measurements of serum PRL revealed low prevalences of marked hyperprolactinemia in ED patients, and intriguingly, very low incidences of pituitary adenomas (0.4%), indicating that other causes of the disease need to be evaluated." (PMID 39085672, 2024). "Risperidone is one of the atypical neuroleptics can induce hyperprolactinaemia, while other atypical drugs are infrequently or transiently increase of PRL levels." (PMID 39663784, 2024). "A link between PRL and the skin was recently highlighted in a patient with thoracocervicofacial purpura and unwitnessed syncope, where hyperprolactinaemia helped establish the diagnosis of an epileptic seizure." (PMID 39000207, 2024). "The clinical presentation of PRLomas results from direct prolactin (PRL) action, duration and severity of hyperprolactinemia, and tumor mass effect." (PMID 38370355, 2024). "Hyperprolactinemia is defined by a serum prolactin level above the reference value for the normal population." (PMID 38578472, 2024). "Testosterone levels were reduced in 16 out of 20 male patients, as expected in presence of hyperprolactinemia, and normalized following prolactin decrease induced by cabergoline." (PMID 38902646, 2024). "In particular, 3 patients with drug-induced hyperprolactinemia had prolactin concentrations above 500 ng/mL, reaching 720 ng/mL in a patient who was taking domperidone and also harbored a 0.5 cm nonfunctioning pituitary microadenoma." (PMID 39420933, 2024). "While some guidelines consider a single PRL measurement sufficient for the diagnosis of hyperprolactinemia (HP), others recommend serial PRL measurement when inconsistencies are detected in clinical findings." (PMID 39552974, 2024). "PRL promotes glucose homeostasis by increasing β‐cell mass under certain conditions such as pregnancy, whereas hyperprolactinaemia due to a pituitary gland adenoma tumour exacerbates IR." (PMID 39663784, 2024). "A continuously elevated prolactin level beyond the normal range for any reason is known as hyperprolactinemia." (PMID 38505795, 2024). "Serum prolactin levels should only be measured in patients with symptoms suggestive of hyperprolactinemia, including galactorrhea, menstrual irregularity, infertility, or decreased libido." (PMID 38578472, 2024). "Data regarding the presence of a prolactin (PRL) threshold above which a pituitary magnetic resonance imaging (MRI) is mandatory in patients with hyperprolactinemia (hyperPRL) are controversial and derived primarily from studies focused on female populations." (PMID 38194218, 2024). "The prolactin levels in patients with hyperprolactinemia due to other etiologies (n = 14) ranged from 46 to 226 ng/mL (mean, 113.76 ± 61.87 ng/mL; median, 86.5 ng/mL)." (PMID 39420933, 2024). "Hyperprolactinemia favours the intraocular incorporation of PRL and its proteolytic conversion to vasoinhibin which, in turn, can lead to a reduction in VEGF-induced increase in retinal vasopermeability." (PMID 37673971, 2024). "The effect of the treatment for hyperprolactinaemia and the effect of prolactin lowering medication on endometriosis are additional problems." (PMID 39407928, 2024). "After the observation period of 10–14 months of testosterone treatment, about 20% of the patients revealed elevated PRL levels > 25 ng/mL (hyperprolactinemia), which have been claimed to exert beneficial metabolic effects according to the HomeoFIT-PRL model." (PMID 39857650, 2024). "Patients with hyperprolactinemia but serum concentration of PRL less than five times the upper limit of normal should undergo PRL retesting." (PMID 38370355, 2024).
hyperprolactinemia (continued). "By contrast, in the Brazilian Multicenter Study on Hyperprolactinemia, the highest prolactin level was 490 ng/mL." (PMID 39420933, 2024). "In this light, an innovative metabolic classification into three PRL interval ranges (hypoprolactinemia, normoprolactinemia and hyperprolactinemia) has been recently proposed in the context of the HomeoFIT-PRL." (PMID 39078526, 2024). "There was a statistically significant difference in the value of the prolactin level depending on the drug used in the therapy (χ2 = 21.098; p = 0.002), i.e., oral risperidone most often led to symptomatic and asymptomatic hyperprolactinemia." (PMID 39061992, 2024). "If drug-induced hyperprolactinemia is suspected, a new serum prolactin measurement is recommended three days after discontinuation of the drug, when withdrawal is possible." (PMID 38765533, 2024). "Above these ranges, high serum PRL (hyperprolactinemia), driven by hypothalamo-pituitary diseases and by many pharmacological agents, has an adverse impact on bodily functions including a disruption to the reproductive system." (PMID 38760578, 2024). "The prolactin levels in patients with idiopathic hyperprolactinemia (n = 40) ranged from 52 to 317 ng/mL (mean, 157.50 ± 67.45 ng/mL; median, 161.45 ng/mL)." (PMID 39420933, 2024). "The prolactin levels in patients with hyperprolactinemia due to acromegaly (n = 30) ranged from 37 to 310 ng/mL (mean, 104.17 ± 65.39 ng/mL; median, 75.5 ng/mL)." (PMID 39420933, 2024). "Another interesting finding of our study was the wide variability in prolactin levels in patients with macroprolactinemia or drug-induced hyperprolactinemia." (PMID 39420933, 2024). "The impact of prolactin and hyperprolactinaemia on endometriosis and endometriosis-related infertility has been studied for more than 40 years, but a clear relationship has not been established." (PMID 39407928, 2024). "Drug-induced hyperprolactinemia, particularly from antipsychotics, is a significant contributor to PG, emphasizing PRL’s multifaceted impact on disease progression." (PMID 39797240, 2024). "X-LAG is more commonly linked to hyperprolactinemia than AIP-positive gigantism, the levels of prolactin (PRL) being higher in the case of X-LAG." (PMID 39194755, 2024). "It is estimated that treating hyperprolactinemia with DA agonists leads to the normalization of PRL levels and the return of ovulatory cycles in approximately 80% of patients." (PMID 38396659, 2024). "Most patients with hyperprolactinemia due to other etiologies had prolactin levels < 100 ng/mL, but these levels were also found in 16.5% of patients with microproplactinomas and in 20% of those with idiopathic hyperprolactinemia." (PMID 39420933, 2024). "Hyperprolactinemia is defined when serum PRL levels are higher than reference values for the normal population." (PMID 38765533, 2024). "Risperidone and paliperidone induce hyperprolactinemia by blocking dopamine D2 receptors in the pituitary gland, disrupting dopamine’s inhibitory effect on prolactin secretion." (PMID 38998877, 2024). "Given the serious side-effects of hyperprolactinemia and the possibilities for changing management by lowering dosage or switching to a different antipsychotic, we propose routinely monitoring prolactin levels in patients who are prescribed antipsychotics." (PMID 38352655, 2024). "Mild hyperprolactinemia should be confirmed with another prolactin measurement after excluding venipuncture stress." (PMID 38578472, 2024). "Despite considerable overlap in prolactin levels among the different etiologies of hyperprolactinemia, values > 250 ng/mL allowed a clear distinction between macroprolactinomas and nonfunctioning pituitary adenomas." (PMID 39420933, 2024). "Hyperprolactinemia is typically defined as a fasting serum prolactin level > 20 ng/mL in men and 25 ng/mL in women." (PMID 38338751, 2024).